RN7SL659P (RNA, 7SL, cytoplasmic 659, pseudogene)
Gene: Miscellaneous RNA gene on chromosome 9 (107,811,616 to 107,811,914, reverse strand). Ensembl gene ENSG00000244104.
Homologues: Orthologues: chimpanzee Metazoa_SRP (99% identical), macaque Metazoa_SRP (86% identical), rabbit Metazoa_SRP (62% identical). Paralogues in human: RN7SL2 (80% identical), RN7SL1 (79% identical), RN7SL3 (78% identical), RN7SL47P (77% identical), RN7SL678P (77% identical), RN7SL126P (76% identical), RN7SL45P (76% identical), RN7SL769P (76% identical), RN7SL220P (76% identical), RN7SL321P (76% identical), RN7SL326P (76% identical), RN7SL625P (76% identical), and 702 more.